MROH5 (maestro heat like repeat family member 5 (gene/pseudogene))
Synonyms: FLJ43860
Gene: Protein-coding gene on chromosome 8 (141,433,829 to 141,507,230, reverse strand). Ensembl gene ENSG00000226807.
Genetic constraint (gnomAD): Loss-of-function variants: 10 observed, 10.81 expected, observed/expected ratio (o/e) 0.92, 90% interval 0.57 to 1.55. The upper end of that interval is the gene's LOEUF score, 1.55, which puts it in group 6 of 6, group 1 being the genes least tolerant of losing a copy. Missense variants: 150 observed, 145.51 expected, observed/expected ratio (o/e) 1.03, 90% interval 0.9 to 1.18. Synonymous variants: 51 observed, 49.59 expected, observed/expected ratio (o/e) 1.03, 90% interval 0.82 to 1.3.
Homologues: Orthologues: chimpanzee MROH5 (92% identical), macaque MROH5 (91% identical), dog MROH5 (72% identical), pig MROH5 (69% identical), mouse Mroh5 (66% identical), rat Mroh5 (66% identical). Paralogues in human: MROH1 (22% identical), MROH7 (19% identical), MROH2A (19% identical), MROH2B (18% identical), MROH8 (16% identical), MROH6 (13% identical), MROH9 (13% identical), MRO (5% identical).
Diseases named in the same sentence as MROH5 in open-access papers:
MROH5 is named in the same sentence as 3 diseases in open-access papers, as found by Europe PMC text mining. Sharing a sentence is not in itself a finding about the gene and the disease. The quoted sentences say what the papers report.
neutropenia (1 paper, 2021). A decrease in the number of neutrophils found in the blood. "In conclusion, the association of MROH5 with neutropenia and five other putative biomarkers warrant further investigation for their potential clinical utility." (PMID 34270794, 2021). "We found that MROH5 was significantly associated with neutropenia in MAGMA gene analyses in patients treated with XELOX (P = 6.6 × 10−7) and was independently validated in those receiving XELOX + cetuximab; pooled P = 3.7 × 10−7." (PMID 34270794, 2021). "MROH5 was identified from MAGMA gene analyses as associated with neutropenia at genome-wide significant levels in patients treated with XELOX and was independently validated in those receiving XELOX + cetuximab." (PMID 34270794, 2021). "The association of MROH5 with neutropenia appeared to be due to independent sets of SNPs in patients treated with XELOX (lead SNP rs76380775 OR = 4.8, 95% CI = 2.4-9.5, P = 1.4 × 10−6) as compared to those receiving XELOX + cetuximab (lead SNP rs12056882 OR = 4.4, 95% CI = 1.4-14, P = 1.0 × 10−2)." (PMID 34270794, 2021).
MROH5 also shares sentences with these, for which no sentence is quoted: cardiovascular disease (1 paper); tumour (1).